TNF (tumor necrosis factor)
Diseases named in the same sentence as TNF in open-access papers (continued):
Sharing a sentence is not in itself a finding about the gene and the disease.
breast carcinoma (continued). "We found that wogonoside reduced the mRNA and protein expression of Twist1 in TNF-α-induced MDA-MB-231 and MDA-MB-435 cells, which indicated that the anti-metastatic effect of wogonoside in breast cancer was dependent of Twist1 expression." (PMID 28774312, 2017). "Lastly in this report, we also demonstrate that blocking the TNF pathway, by using the antibody infliximab, increases phagocytosis of MCF7 breast cancer cells mediated by a reduction on CD47 expression." (PMID 28378740, 2017). "Lastly, we blocked BRD4 binding to the CD47 breast cancer SE, by using the inhibitors I-BET151 and PFI-1 and we observed a reduction on TNF-α mediated CD47 upregulation in MCF7 cells." (PMID 28378740, 2017). "Breast carcinomas express elevated levels of cytokines such as transforming growth factor-β (TGF-β) and pro-inflammatory cytokines tumor necrosis factor (TNF) and interleukin 1β (IL-1β)." (PMID 28977919, 2017). "Interestingly, we demonstrated that TNF-α/TNFR1 could up-regulate HBXIP in breast cancer cells." (PMID 28938560, 2017). "Our finding provides new insights into the mechanism by which TNF-α stimulates HBXIP in the link between inflammation and cancer in breast cancer." (PMID 28938560, 2017). "The present meta-analysis investigated the correlation between BRMS1 and the clinico-pathological features of breast cancer including LNM, TNF stages, tumor size, histological grade, pathological type, ER, PR, OS, and RFS." (PMID 28533425, 2017). "Assessment of MMP9 by in-gel gelatin-zymography assays showed that TNF and TGF-β cytokines induced secretion of MMP9 by breast cancer cells and this was further enhanced by co-treatment with both cytokines together." (PMID 28977919, 2017). "Taken together, we conclude that TNF-α is positively related to HBXIP in clinical breast cancer tissues and up-regulates HBXIP in breast cancer cells." (PMID 28938560, 2017). "Therefore, we supposed that TNF-α might be involved in the proliferation of breast cancer cells." (PMID 28938560, 2017). "In MDA-MB-231 breast cancer cells incubated with PsA-D led to a reduction of MCP-1 by 85%, a decrease of TNFα release by 75%, and a decrease of IL-6 by 38%." (PMID 28832545, 2017). "The reporter assay revealed TRIM44 knockdown significantly impaired NF-κB-mediated transcriptional activity stimulated by tumor necrosis factor α (TNFα) in both MCF-7 and MDA-MB-231 breast cancer cells." (PMID 28885545, 2017). "TRIM44 knockdown caused attenuated phosphorylation of the p65 subunit of NF-κB and NF-κB inhibitor α (IκBα) on TNFα stimulation in both MCF-7 and MDA-MB-231 breast cancer cells." (PMID 28885545, 2017). "Human breast carcinoma MCF-7 cells were preincubated with quinacrine for 1 h and then incubated with TNF-α for 6 h." (PMID 29207489, 2017). "IL-18 added to IL-2 increases Vγ2Vδ2 T cell numbers by 2.7-fold after zoledronate stimulation of PBMC from breast cancer patients and increases the production of IFN-γ and TNF-α." (PMID 28239463, 2017). "MK2i also sensitized human breast cancer BT549 and MDA-MB-468 cells to TS, implying that MK2 inhibition sensitizes to TNF-induced cell death in general." (PMID 28506461, 2017). "Moreover, TNF-α could up-regulate HBXIP in breast cancer cells." (PMID 28938560, 2017). "It has been known that TNF-α promotes EMT by up-regulating transcription factors such as Twist1/2, Snai1/2 and Zeb1/2 in renal cell carcinoma, breast cancer cell and colon cancer cell." (PMID 28550311, 2017). "It has been shown that TNF-α and/or IFN-γ stimulated MUC16 mRNA levels in a dose dependent manner in ER positive breast cancer cells." (PMID 29202842, 2017).
breast carcinoma (continued). "Mechanistically, macrophage conditioned medium (CM) or TNFα triggers IκB kinases (IKKs)-mediated YAP phosphorylation and activation in breast cancer cells." (PMID 28945218, 2017). "Collectively, we conclude that TNF-α increases STAT3 phosphorylation via NF-κB and/or p38 signaling in activation of HBXIP promoter in breast cancer." (PMID 28938560, 2017). "As demonstrated for melanoma, neuroblastoma and breast cancer, the transcription of the GD3 synthase gene (ST8SIA1) is activated by NF-κB pathway upon TNF stimulation." (PMID 27916834, 2016). "In conclusion, these data suggest that intratumoral delivery of TNF-α preactivated MSCs immediately after single dose irradiation could be a potential strategy for cancer treatment through the strongest antitumor effects as well as significant suppressive action on metastasis of breast cancer." (PMID 27329316, 2016). "Characteristics of breast cancer controls (n = 885) across levels of several inflammation markers (ox-LDL, TNF-α, and IL-1β) in the Malmö Diet and Cancer cohort." (PMID 27391324, 2016). "Pro-inflammatory cytokines TNF-α and IFN-γ also enhanced the expression of MUC1 in breast cancer cells through NF-κB and signal transducer and activator of transcription 1 (STAT1) activation, respectively." (PMID 27754373, 2016). "However, another report identified that Wnt5a could induce invasiveness of cancer cells and the production of matrix metalloproteinase-7 (MMP7) and tumor necrosis factor-α (TNF-α) in macrophages, which was essential for macrophage-induced invasiveness in breast cancer." (PMID 27895670, 2016). "In an in vitro murine breast cancer cell line, it has been demonstrated that the combination of the Th1 cytokines IFN-γ and TNF-α inhibit cell growth, increase apoptosis, and downregulate HER-2 surface receptor expression." (PMID 27766079, 2016). "It is therefore conceivable that de novo synthesis of TNFα, via the canonical NF-κB pathway, is the primary effect of TPA treatment in MDA-MB-468 breast cancer cells." (PMID 27551497, 2016). "Here, we found that exogenous TNF-α enhances the accumulation of both MT1-MMP and CD26 and, additionally, FAP-α in lipid rafts in different breast cancer-derived cells." (PMID 27042827, 2016). "Inflammatory cytokines including interleukins (IL-1β, IL-2, IL-6, IL-8, IL-12), tumor necrosis factor alpha (TNF-α), and interferon gamma (IFN-γ) are key inflammatory mediators of interest in breast cancer progression." (PMID 26970739, 2016). "Many cells increase their proteolytic activity in response to inflammatory cytokines, such as tumor necrosis factor α (TNF-α), which is frequently upregulated in human epithelial malignancies such as breast cancer." (PMID 27042827, 2016). "In this study, we exposed Luminal-A breast cancer cells in culture to combined “TME Stimulation”, representing three typical arms of the breast TME: hormonal (estrogen), inflammatory (tumor necrosis factor α) and growth-promoting (epidermal growth factor)." (PMID 27835603, 2016). "We assessed the effect of morphine on the production of IL-6, TNF-α and VEGF-A by macrophages and breast cancer cells grown individually or co-cultured in a transwell." (PMID 27514308, 2016). "IL-1β induced IL-6 production in breast cancer cells in a TG2-dependent manner, and other cytokines and growth factors including TGF-β, TNF-α, and EGF potentiated the effect of IL-1β on IL-6 expression." (PMID 27609180, 2016). "As positive control, we used MDA-MB-231 breast carcinoma cells, as we previously reported that they undergo apoptosis upon treatment with BV6 in a TNFα-dependent manner." (PMID 26575016, 2015). "PBMCs from breast cancer patients were stimulated overnight through the T-cell receptor with anti-CD3 and anti-CD28 antibodies and interrogated for intracellular TNF-α synthesis by multiparameter flow cytometry." (PMID 26207636, 2015).
breast carcinoma (continued). "Tumor necrosis factor-α (TNF-α) and TGF-β, which are secreted from breast cancer cells, induce the expression of MMP-9 in fibroblasts." (PMID 26690480, 2015). "The proinflammatory cytokines and chemokines secreted by macrophages and adipose cells, including TNF-α, IL-6, MCP-1 and leptin, can directly stimulate breast cancer cell proliferation and invasion." (PMID 26132316, 2015). "The co-administration of mesna with Dox reduced plasma levels of TNF-α, TNFR1 and TNFR2 compared to saline for patients with high baseline values receiving Dox for breast cancer and NHL." (PMID 25909710, 2015). "COX-2 is involved in carcinogenesis of colorectal and breast cancer, and activation of PPARγ by specific ligands eliminates COX-2 expression induced by tumor necrosis factor (TNF)-α." (PMID 25734181, 2015). "In particular, tanshinone I inhibits growth, invasion and angiogenesis on human breast cancer cells MDA-MB-231, both in vitro and in vivo, by decreasing the TNF-induced VEGF production." (PMID 26553968, 2015). "A positive feedback loop has been demonstrated in mouse mammary tumours whereby the cancer cells release MCP-1; this promotes macrophage secretion of TNF-α, which in turn promotes further MCP-1 expression by cancer cells." (PMID 25588705, 2015). "In breast cancer, MMP-9 activity has been localized around CAFs and CAFs co-cultured with cancer cells which secrete TGF-β, TNF-α, and other cytokines, increase production of MMP-9, consistent with our in vitro data." (PMID 24586907, 2014). "In conclusion, the present study has demonstrated the potential of BZYQ in alleviating paclitaxel chemotherapy-related fatigue by reducing the serum level of TNF-α and modulating the levels of MDA and SOD activity in the 4 T1 murine breast cancer model." (PMID 25511260, 2014). "In this study, we examined the combinational associations of serum levels of 25OHD with plasma levels of three cytokines, IFNα2, TNFα and IL5, as well as ten cytokine ratios, on ER status of breast cancer." (PMID 24473087, 2014). "Similar gene expression results were found in control MG and breast cancer (BC) samples, with heterogeneous levels of GRP-F1, MGP, GGCX, and VKOR and increased expression of OPN and TNFα in cancer cases." (PMID 24949434, 2014). "Previous study provided a significant correlation between TNF-α expression and the expression of putative TNF-α-inducible NF-κB-related genes in human breast cancer." (PMID 24864130, 2014). "Increased TNFα and MCP-1 expression can promote breast cancer progression, through direct binging to the TNF receptor and through recruitment of macrophages to tumor sites, respectively." (PMID 24994117, 2014). "Additional research in other breast tumor systems should be taken in order to substantiate these mechanisms, as they may have a significant impact on therapeutic approaches for the treatment of cases of breast cancer in which the tumors express high levels of TNFα and Ras is generally not mutated." (PMID 24598028, 2014). "The “combined stimulation” approach is supported by published findings demonstrating coregulatory intracellular interactions existing between TNFα-, estrogen-, and/or EGF-mediated pathways in breast cancer and in other malignancies." (PMID 24369447, 2013). "Costunolide further suppressed TNFα-induced NF-κB signaling activation, resulting in a reduced expression of MMP-9, a well-known NF-κB-dependent gene to mediate breast cancer cell growth and metastases." (PMID 23997800, 2013). "Therefore, we conclude that SLC and its derivative costunolide suppress breast cancer growth and metastases by inhibiting TNFα-induced NF-κB activation, suggesting that costunolide as well as SLC may be promising anticancer drugs, especially for metastatic breast cancer." (PMID 23997800, 2013). "It has been shown that TGF-β inhibited TNF-α-induced CXCL1 release in human ECs and TGF-β regulated suppression of inflammatory genes such as CXCL1 and CXCL5 in mammary carcinoma cells." (PMID 23665907, 2013).
breast carcinoma (continued). "CD44V4, a major E-selectin ligand for breast cancer cells, was found to be upregulated on MDA–MB-231 cells treated with TNF-α." (PMID 23372803, 2013). "To further confirm the inhibition of VEGF production in breast cancer cells, we measured the level of VEGF in MDA-MB-231 cells that were first treated with various concentration of OME and then stimulated with TNF-α." (PMID 23874773, 2013). "The mechanisms of differential responses of breast cancer cell lines to combined treatment with anti-HER2 antibody and TNF-α merit further investigation." (PMID 23033967, 2012). "Whereas high expression of TNF-α was therefore correlated with diminished IGF-IR levels, our work showed that silencing IGF-IR in the C4HD breast cancer model increased TNF-α and IFN-γ secretion." (PMID 22235273, 2012). "In breast cancer patients, depressed serum levels of IL-2, GM-CSF, IFN-γ and enhanced TNF-α and IL-6 amounts were reported in comparison with controls and some of these immune dysfunctions are also present in early-stage tumors." (PMID 22112244, 2011). "Recently, much attention has been given to the roles of inflammatory chemokines and cytokines in breast cancer, with emphasis on the chemokines CCL2 and CCL5, and the cytokines tumor necrosis factor α (TNFα) and interleukin 1β (IL-1β)." (PMID 21486440, 2011). "Deletion of ST2 in BALB/c mice bearing mammary carcinoma attenuated tumor growth and metastasis, which was accompanied by increased serum levels of IL-17, IFN-γ, and TNF-α and decreased IL-4." (PMID 21484786, 2011). "A recent report implicates novel gene sets in oncogenic Ras, TNF and IFN pathways in breast cancer CD44+/CD24−/low populations." (PMID 21079774, 2010). "Both TNF-α and TGF-β have been reported to suppress breast cancer cell proliferation, predominantly against ER-positive cells." (PMID 19190628, 2009). "Generating DCs from CD14+monocytes using GM-CSF, IL-4 and maturing them with TNF-α ± IFN-α (DCT and DCTI) is a novel strategy which was based on our previous work using monocytes from patients with operable breast cancer." (PMID 19298672, 2009). "More recently, we showed that goserelin administration produces the regression of NMU-induced mammary tumors through the inhibition of prolactin (PRL), tumor necrosis factor (TNF)-alpha and nitric oxide expression." (PMID 19491505, 2009). "Additional studies are needed to clarify the functions and involvement of these proteins in the mechanisms of MEK5/Erk5-mediated TNF-α resistance and EMT in human breast cancers." (PMID 19087274, 2008). "Taken together, we suggest that TNF-α-induced MMP-9 expression and cell invasion are decreased by BBR through the suppression of AP-1 DNA binding activity in MDA-MB-231 human breast cancer cells." (PMID 19052522, 2008). "Evidence for the antiapoptotic function of p21 has been provided in TNF-α induced cytotoxicity in Ewing tumor and MCF-7 breast carcinoma cell line, in differentiation induced apoptosis of monocytes and CD95 mediated cell death in human glioma cell lines." (PMID 17565690, 2007). "By lowering the ERα protein level, TNFα and PI3-kinase can overcome transrepression by ERα, thus promoting invasion and metastasis of breast cancers." (PMID 14970864, 2004). "The expression of tumour necrosis factor alpha (TNF-alpha) and its two distinct receptors, TNF-R p55 and TNF-R p75, was assessed by immunocytochemistry in 28 primary breast cancer and three reduction mammoplasty specimens ('normal' breast tissue)." (PMID 7519867, 1994). "Our findings highlight the immune-editing role of stress-programmed Effector regulatory T cells, Neoadjuvant chemotherapy, Stress-programmed immune states, TNF α -TNFR2 axis, breast cancercell states and support their therapeutic potential as a rational target in breast cancer." (PMID 41486103, 2026).
breast carcinoma (continued). "Breast cancer cells can directly stimulate osteoclastogenesis by secreting factors such as receptor activator of nuclear factor kappa-Β ligand (RANKL), IL-1, IL-6, and tumor necrosis factor-alpha (TNF-α)." (PMID 40444046, 2025). "The results showed that CBD, THC, and HL significantly decreased TNF-α concentration in the blood of the DMBA-induced breast cancer model rats, but the changes were not significant." (PMID 40008130, 2025). "Several in vitro studies report that sea buckthorn extracts from seeds, berries, leaves, or juice inhibit breast cancer cell proliferation and induce apoptosis via mechanisms such as CASP3, IGFBP4, GADD34 modulation, cell cycle arrest, and TNF–NF‐κB signaling inhibition." (PMID 41409192, 2025). "Moreover, we also found that this strategy played an important role in reducing the levels of inflammatory biomarkers (TNF-α and CRP) in breast cancer patients." (PMID 40289959, 2025). "Additionally, KLF5 expression is reduced in prostate cancer, leading to the inhibition of angiogenesis, whereas in breast cancer, KLF5 promotes angiogenesis by binding to the promoters of tumor necrosis factor (TNF)α-induced protein 2 (TNFAIP2)." (PMID 40038579, 2025). "Additionally, DIM was found to modulate Smad and non‐Smad signaling pathways induced by TNF‐α/TGF‐β, indicating its role in suppressing EMT markers and potentially inhibiting breast cancer metastasis." (PMID 40584407, 2025). "Lymphocytes suppress breast cancer progression through immune surveillance mechanisms, including mediating cytotoxic apoptosis of tumor cells and secreting anti-tumor factors such as interferon-γ (IFN-γ) and tumor necrosis factor-α (TNF-α)." (PMID 40909265, 2025). "Christodoulatos et al186 discovered an independent negative correlation between plasma omentin-1 levels and breast cancer incidence in a postmenopausal cohort and inflammatory markers (TNF-α, IL-6)." (PMID 40584290, 2025). "Subgroup analysis demonstrated a non-significant influence of propolis consumption on the TNF-a levels in the trials conducted on only females, subjects aged < 50 years, and participants with breast cancer, NAFLD, and type 2 diabetes." (PMID 40421039, 2025). "From a therapeutic standpoint, TNF-α is a validated target in inflammatory diseases, but TNF-α inhibitors have not yet shown benefit in breast cancer." (PMID 41007766, 2025). "A clinical study of breast cancer tissue specimens showed that compared to adjacent non-cancerous tissues, the mRNA and protein expression levels of tumor necrosis factor alpha (TNFα), RIPK1, RIPK3, and MLKL were significantly elevated in breast cancer tissues." (PMID 41346619, 2025). "Interestingly, Bcl3 played a protective role against TNF/CHX-induced apoptosis in colon cancer cells and breast cancer cells." (PMID 40015625, 2025). "TNF-α also coordinates with TGF-β to induce EMT in multiple cancer types, including breast cancer." (PMID 40833805, 2025). "TGM2 expression was also increased in MCF7 (breast cancer), DU145 (prostate cancer), and A549 (lung cancer) cell lines in response to two other EMT-inducers TNFα and EGF, demonstrating that increased TGM2 expression is consistently associated with the EMT process." (PMID 40777010, 2025). "In breast cancer cell line MCF-7-MEK5 with stably EMT property, FAS was able to regulate the sensitivity of tumor necrosis factor-α (TNF-α) through modulating TNF receptor 2 (TNFR2) via lipid rafts and activating Wnt-1/β-catenin signaling pathway that closely involves in EMT." (PMID 41019990, 2025). "In contrast, luminal (ER+) breast cancer cells exhibit significantly increased sensitivity to TNFα-induced cell death in the absence of A20, which was prevented by A20 overexpression via activating the HSP70-mediated anti-apoptotic pathway." (PMID 40214497, 2025).